PRR20B (proline rich 20B)
Tractability: No criterion of Open Targets' tractability assessment is met for any kind of drug.
Gene: Protein-coding gene on chromosome 13 (57,147,488 to 57,150,509, forward strand). Ensembl gene ENSG00000204918.
Homologues: Orthologues: dog PRR20G (38% identical). Paralogues in human: PRR20A (100% identical), PRR20C (100% identical), PRR20D (100% identical), PRR20E (100% identical), PRR20G (53% identical).